CCL7 (C-C motif chemokine ligand 7)
Diseases named in the same sentence as CCL7 in open-access papers (continued):
Sharing a sentence is not in itself a finding about the gene and the disease.
tumor (continued). "In general, CCL7 has been shown to play dual roles in cancer progression by promoting the recruitment of immune cells such as NK cells, DCs, and macrophages into the tumor microenvironment as well as cancer metastasis." (PMID 33777801, 2021). "Ccl2 and Ccl7 (also known as monocyte chemoattractant protein 1 and 3, respectively) play a critical role in the recruitment of monocytes and neutrophils to the inflamed or tumor tissue, while Ccl17 attracts regulatory T cells." (PMID 34504786, 2021). "The tumor-promoting chemokine CCL7 is also more abundantly secreted by M-MΦs than GM- or R-MΦs." (PMID 34771453, 2021). "We observed the concomitant expression of anti-tumor factors (Il1b, Il13, Ccl7, Il2)." (PMID 34578328, 2021). "Among the cytokines secreted by CAFs, CCL7 is known to be tumorigenic, which may promote tumor growth, invasion, and metastasis." (PMID 33175885, 2020). "However, in this setting, we cannot totally exclude that the tumor cell lines, upon interaction with the LECs, also increase their CCL7 secretion." (PMID 31963450, 2020). "In addition, combinational treatment of CCL7 and anti-PD-1 was superior to anti-PD-1 alone in regard to the survival and tumor development in lungs of KP or KL mice." (PMID 33257678, 2020). "CCL7 deficiency impairs the infiltration of cDC1 in the TME and the subsequent expansion of CD8+ and CD4+ T cells in bronchial draining lymph nodes and TME, thereby promoting tumor development in the KP mouse model." (PMID 33257678, 2020). "Similarly, CCL7 injection significantly prolonged the survival and inhibited tumor development of the KP or KP7 mice compared to the respective controls." (PMID 33257678, 2020). "Consistently with these observations, the numbers of infiltrating cDC1 and the intensities of CD11c, XCR1 and CD8 staining were significantly increased in the tumor-burdened lungs of KP or KP7 mice injected with CCL7 compared to those injected with control viruses." (PMID 33257678, 2020). "Expectedly, CCL7 significantly promoted the infiltration of cDC1 in the tumor-burdened lungs." (PMID 33257678, 2020). "However, overexpression of CCL7 in tumor cells has been reported to promote tumorigenesis by facilitating tumor cell proliferation and metastasis or retain tumor growth by recruiting immune cells into tumors in exogenous mouse models." (PMID 33257678, 2020). "Because CCL7 is a chemotactic factor for various immune cells such as monocytes and DCs, we analyzed the percentages and numbers of the myeloid cells infiltrated in the tumor-burdened lungs of KP and KP7 mice at 10 weeks after induction." (PMID 33257678, 2020). "Moreover, lungs from CCL7-overexpressing tumor-bearing mice had severe intra-alveolar bleedings, which were absent in the case of the control mice." (PMID 30764543, 2019). "Changes in expression levels of factors known to modulate tumor growth through immune recruitment (ie, CCL7, CCL8, ICAM) by resistance to death (ieTrxR, Trx, HIF‐1), and metastasis (ie, MMPs, ADAMs, ILs, Cts) may drive the inhibition observed." (PMID 31192543, 2019). "Low let-7d expression levels and high CCL7 levels predict advanced T stage and high tumor grade." (PMID 29915688, 2018). "Furthermore, in high-grade metastatic RCC, upregulated expression of CCL7 is particularly prominent, and let-7d is apparently downregulated, which emphasizes the significance of CCL7 in tumor invasion and metastasis." (PMID 29915688, 2018). "CCL7 is expressed in various types of cells under physiological conditions, including in stromal cells, airway smooth muscle cells, and keratinocytes, and in tumor cells under pathological conditions." (PMID 29915688, 2018). "CCL7 can act as a tumor-derived factor that may promote tumor growth, invasion and metastasis in an autocrine manner." (PMID 29915688, 2018).
tumor (continued). "CCL7 promotes tumor progression by supporting the formation of the tumor microenvironment and facilitating tumor invasion and metastasis, although some studies have suggested that CCL7 has tumor suppressor effects." (PMID 29915688, 2018). "CAFs behave in a collaborative manner with CCL7 to influence tumor migration." (PMID 29915688, 2018). "Chemokines such as CCL2, CCL5, CCL7, CCL8, CXCL12 and growth factors, for example, M-CSF, PDGF, and VEGF aggressively recruit blood monocytes at the tumor site, where they distinguish in tumor-associated macrophages." (PMID 29450136, 2017). "Additionally, IFNβ induces expression of CCL2, CCL7 in tumor cells, as well as CCL12 in host cells at the transcription level." (PMID 29170400, 2017). "CCL7 has been identified as a monocyte attractant produced from certain tumor cells and macrophage, and shown to function as a chemotactic for eosinophil infiltration into the lung tissues in TH2-type pulmonary granuloma, which was blocked by anti-IL-4 treatment." (PMID 27010397, 2016). "To confirm these in vitro findings, we tested whether CCL7 overexpression could enhance tumor growth in vivo using a mouse xenograft model." (PMID 27167205, 2016). "To confirm these in vitro findings, we investigated whether CCL7 could enhance tumor growth and metastasis in vivo using ectopic and orthotopic mouse model system." (PMID 27167205, 2016). "Therefore, the gradient of CCL7 found in PPAT will be able to promote the directed migration of invasive tumour cells expressing the CCR3 receptor." (PMID 26756352, 2016). "As a chemoattractant, CCL7 facilitates the migration and accumulation of monocytes and macrophages through its specific receptors and plays a role in various physiological processes, including cell migration, immune response, inflammation, and tumor development." (PMID 39334887, 2024). "It has extensively been reported that these anti-tumour drugs impact the tumour microenvironment (TME), target human tumour-associated macrophages (hTAM), and inhibit the transcription of pro-inflammatory cytokines such as CCL2 (chemokine ligand 2), IL-6, VEGF, CCL3, CCL7, and CCL14." (PMID 38257245, 2024). "Meanwhile, the authors also observed the moderate reduction of Tregs number in Fmr1−/‐ Ccl7−/− group, but no change in the expression of tumor‐associated macrophages (TAMs) markers involved in immunosuppression, indicating that CCL7 was only involved in the regulation of inflammation by T cells." (PMID 36968189, 2023). "Ccl7 and Ccl9 may also facilitate tumor progression and metastasis." (PMID 37954069, 2023). "Thus, knockdown of IL-1β and CCL7 etc. were insufficient to inhibit tumor invasion." (PMID 36045118, 2022). "Notably, Osmrhigh CAFs express higher levels of inflammatory signals such as Il6, Ccl7, Ccl2 and Cxcl1 in animal models of PDA, OSMR is expressed at increased levels in human PDA and is associated with a tumour-promoting immune infiltrate and worse patient outcome." (PMID 34921158, 2021). "Importantly, treatment of JAK1 inhibitor in KP mice significantly downregulated the mRNA levels of Ccl7 in the lungs at 8 weeks after tumor induction, suggesting that CCL7 is upregulated in the tumor-burdened lungs in KP mouse model in a JAK-STAT-dependent manner." (PMID 33257678, 2020). "Finally, an in vivo study revealed that subcutaneous injection of CT26 cells overexpressing CCL7 led to acceleration in the early phase of tumor growth (between day 5 to day 11) when mCCL7+ tumor-bearing mice had bigger tumor size when compared with blank control-injected mice." (PMID 30764543, 2019). "Our analysis showing higher CCL5 and CCL7 in BrCa tissues compared to normal tissues indicates that BrCa cells which produce high levels of CCL5 and CCL7 could be responsible for recruiting monocytes in the tumor microenvironment and supporting BrCa progression." (PMID 30850664, 2019).
tumor (continued). "Within the tumor microenvironment, gene expression profiling revealed upregulated chemokine signaling pathways (CCR2/CCL7, CXCR6/CXCL16) and key immunosuppressive markers, including PD-L1 and TGF-β1." (PMID 42227811, 2026). "This review compiles current knowledge on the significance of lesser-known chemokines in MM tumor processes, including CXCL13, CCR2 ligands (CCL2 [MCP-1], CCL7 [MCP-3]), CCL4, CCL5 (RANTES), CCL17, CCL20, CCL27, CCL28, and CX3CL1 (fractalkine)." (PMID 41749925, 2026). "Taken together, these data demonstrated that ZBP1 enhanced tumor cell invasiveness and metastatic potential by regulating CAF-secreted CCL7 to activate CCR1-dependent signaling pathways." (PMID 41430036, 2025). "The CCL chemokines CCL2, CCL7, CCL8, and CCL12 are known ligands for CCR2 expressed on circulating monocytes and facilitate their recruitment into the tumor microenvironment." (PMID 40867322, 2025). "In glioblastoma, LDHA activates the ERK-YAP1/STAT3 axis, upregulating CCL2 and CCL7 to recruit macrophages, which in turn deliver LDHA to tumor cells via extracellular vesicles, forming a tumor-macrophage symbiotic loop that drives progression." (PMID 40734168, 2025). "HIF-1α also regulates downstream targets like CCL7 and KIAA1199, forming a HIF-1α/CCL7/KIAA1199 axis that accelerates glycolysis and promotes tumor progression." (PMID 41220952, 2025). "Both CCL2 and CCL7 serve as ligands for the chemokine receptor CCR2 17, which was found to be overexpressed in TRPC tumor infiltrates." (PMID 40661379, 2025). "As verified by exocytotic chemokines, the expression of tumor-promoting chemokines, including CCL3, CCL5, CCL7, CCL11, CXCL1, and CXCL12, showed a downward trend after MWA." (PMID 38779358, 2024). "High expression of CCL7, a natural antagonist for CCR5, demonstrates the role of APOC1+ TAMs in inhibiting the mobility of CD8+ T cells, thus suppressing tumor immune responses." (PMID 39232806, 2024). "Tumor-resident mesenchymal stem cells, known for their significant secretion of a variety of chemokines, including CCL-2, CCL-7 and CCL-12, enhance the recruitment of CCR2-expressing monocytes to tumor sites, thereby increasing the macrophage population." (PMID 38575562, 2024). "Another study showed that PPAT secretes the chemokine CCL7, which diffuses from PPAT into the peripheral zone of the prostate and stimulates the migration of CCR3-expressing tumor cells." (PMID 38164282, 2024). "After irradiation, tumor cells activate the STING/IFN-β signaling pathway to release chemokines, including CCL2, CCL7, and CCL12, via the CCR2 pathway to recruit M-MDSC." (PMID 39464890, 2024). "GBM cells induce macrophages to infiltrate the tumor microenvironment by upregulating CCL2 and CCL7, and then macrophages promote tumor growth and survival by delivering LDHA to tumor cells." (PMID 39493751, 2024). "IFN-β, a downstream signal of the cGAS-STING signaling pathway, can also stimulate tumor cells to produce CCL2 and CCL7 and affect the recruitment of M-MDSC." (PMID 39464890, 2024). "The interaction between ACKR2 and CCL13, CCL7 illustrates that SLC40A1+ TAMs and APOC1+ TAMs be recruited by ECs to modulate tumor immunity." (PMID 39232806, 2024). "Among them, Macro-2 seems to be a key player in the tumor metastatic cascade, characterized by expression of SPP1, CCL18, CXCL5, CCL2, and CCL7." (PMID 38281962, 2024). "TAM recruitment is particularly important and CCL7 and CCL8 can also attract tumour-infiltrating lymphocytes." (PMID 39146303, 2024). "Bidirectional crosstalk between tumor cells and CAFs enhances the ability of fibroblasts to secrete various pro-tumor chemokines, including CXCL12/CXCR4 axis, CCL2, CCL5, CCL7, CXCL8, and CXCL14." (PMID 39092186, 2024). "The recruitment of tumor-associated macrophages (TAMs) to tumor sites is mediated by chemokines such as CCL2, CCL5, CCL7, CXCL1, CXCL2, and CXCL4, which promote tumor survival." (PMID 39769501, 2024).
tumor (continued). "At the same time, extracellular tumor-promoting chemokines, such as CCL3, CCL5, CCL7, CCL11, CXCL1, and CXCL12, were also downregulated." (PMID 38779358, 2024). "Targeting both CCL2/CCR2 and CSF-1/CSF-1R axis is therefore relevant to a tumor that overexpresses M-CSF, CCL2 and other chemokines that bind to CCR2 such as CCL7." (PMID 38076998, 2023). "The levels of cytokines CCL21, eotaxin, CXCL1, CXCL2, CCL7, CCL19, and CCL25, which are capable of supporting tumor invasion, were reduced in CM from MSCs-TRAIL by 1.2, 1.3, 4-8, 3.4-1.3, 1.5, and 1.3 times, respectively (n = 3, ** p < 0.01)." (PMID 36661524, 2023). "Tumor cells secrete chemokines (CCL2, CCL7, and CXCL12) and cytokines (VEGF) to recruit peripheral blood monocytes into tumor tissues and induce them to differentiate into TAMs." (PMID 37064113, 2023). "Double immunofluorescence microscopy showed that tumor-infiltrating CD11c+ cells were positive for CCR1 and CCR2 (receptors of CCL7) in the control group." (PMID 37046033, 2023). "In KP mouse model, depletion of CCL7 destroyed the conventional DC 1 infiltration in the TME and promoted expansion of CD4+ and CD8+ T cells in TME, resulting in tumor development." (PMID 37033636, 2023). "These monocytes and macrophages in luminal tumor hubs upregulate inflammation (MMP12 and MMP9), myeloid cell recruitment (CCL2 and CCL7), and tumor growth–promoting genes (VEGF and EREG)." (PMID 37492581, 2023). "Although CCR1, CCR2, CCR3, and CCR5 are widely recognized as the main functional receptors of CCL7, PCa is mainly dependent on the CCR3/CCL7 signaling axis, which contributes to the tumor microenvironment." (PMID 35406450, 2022). "The levels of six cytokines differed among groups, including significant elevations in aged DIO mice, relative to the other groups, in the tumor-promoting chemokines CXCL13, CCL7, and CCL11." (PMID 36686775, 2022). "For the cirReNET we built, there were many targeted genes involved in the mechanism of tumor genesis, such as AKT1, ErbB2, ITGB7, BAX, MAPK, FBXL12, CCL7 and so on." (PMID 35611168, 2022). "Four hub mRNAs in this network, including CXCL10, CXCL11, CCL7, and CCL8, were identified which have also been demonstrated to influence the tumor microenvironment and infection status." (PMID 36544484, 2022). "Taken together, these results suggest that bone marrow-derived CCR2+/CX3CR1+ cells from naïve and tumor-bearing animals migrate to CCL2 and CCL7, in a CCR2-dependent manner." (PMID 36685592, 2022). "In general, our study identified KLF15 as a tumor suppressor in TNBC, and illustrated that KLF15 suppresses TNBC proliferation and metastasis by targeting and downregulating CCL2 and CCL7." (PMID 36347994, 2022). "Influenced by the tumor microenvironment, and through the production of specific chemokines such as CCL-2, CCL-7 or CCL-12, MSCs are able to recruit CCR2 expressing monocytes to tumor sites, promoting the local concentration of macrophages and tumor growth." (PMID 35214113, 2022). "And IL-33 can stimulate the production of cytokines (IL-4, IL-6) and chemokines (CCL2, CCL3, CCL7, CXCL1), which are also involved in the construction of the tumor microenvironment." (PMID 36110250, 2022). "Collectively, a LINC01094/SPI1/CCL7 axis was defined in LUAD, which is potentially linking to macrophage infiltration and tumor development." (PMID 36118415, 2022). "The chemokines CCL2 and CCL7, which are known as ligands of CCR2, promote the invasion and metastasis of tumor cells and induce immunosuppression." (PMID 35320940, 2022). "Additional studies aimed toward determining specific CCL2-, CCL7-, and CX3CL1-expressing areas and cell types within the tumor would need to be conducted to support these concepts." (PMID 36685592, 2022). "Interaction between CCL7 and its ligand CC-chemokine receptor 3 (CCR3) will allow tumor migration outside of prostatic gland and initiate metastatic process." (PMID 34354670, 2021).
tumor (continued). "Moreover, CXCL10, CXCL12, and CCL7, which may promote tumor progression, were also highly induced." (PMID 34771453, 2021). "CCL7 secreted by Mo-MDSCs binds to CCR2 of dormant cells and promotes the transition from tumor dormancy to metastatic outgrowth through the JAK-STAT3 signaling pathway." (PMID 33986252, 2021). "Previous studies have reported that CCL7 can combine with CCR2 to activate the STAT3 signal pathway and thus promote tumor cell metastasis." (PMID 33986252, 2021). "For instance, CAF‐secreted chemokines like CCL7 and CXCL16 strongly induced the activation of TGF‐β pathway in HCC, which significantly accelerated tumour metastasis." (PMID 33713546, 2021). "Proinflammatory pathways are upregulated in KRAS-dependent tumors, including increased production of the chemokines IL-1β, CCL7, and CCL2, as a result of crosstalk between KRAS-mutant tumor cells and host myeloid cells." (PMID 33335263, 2020). "Ccl7 (also called MCP3) plays a crucial role in cancer as it can promote tumor growth, tumor microenvironment, invasion and metastasis." (PMID 32659965, 2020). "The expression of chemokines for CCR2 (Ccl2 and Ccl7) or CCR5 (Ccl3, Ccl4, and Ccl5) in tumor-bearing lungs, chemoattractants for monocytes/macrophages, was unchanged in FROUNT-cKO mice." (PMID 32001710, 2020). "TAM recruitment can also be induced by CCL7 and CCL8, while Treg are recruited into the tumor niche by CCL8 into the tumor niche." (PMID 33182504, 2020). "Since CCL7 is upregulated in NSCLC tumor tissues and positively correlated with the OS of NSCLC patients, we investigated the role of CCL7 in primary NSCLC development with the KP mouse model." (PMID 33257678, 2020). "We found that reactive CAFs induce resistance to FSS to tumor cells by forming a protective cellular nodule and by soluble factors such as: CCL2, CCL7 and CXCL5." (PMID 32256977, 2020). "Tumor-resident MSCs release a large amount of various chemokines, including CCL-2, CCL-7 and CCL-12, thereby enhancing the recruitment of monocytes expressing CCR2 into tumor sites and increasing the number of macrophages and growth of tumors." (PMID 31336889, 2019). "Classically, it is dependent on bloodstream-derived monocyte infiltration mediated by CCL2, CCL7, CXCL12, VEGF, and other cytokines produced in the tumor microenvironment by stromal and tumor cells." (PMID 31275860, 2019). "Evidence indicates, for example, that chemokines such as CCL5, CCL7, CXCL8 act via CCRs on myeloid-derived suppressor cells (MDSCs) to form an inhibitory tumor microenvironment that promotes tumor pathogenesis, progression and resistance." (PMID 30631005, 2019). "Local radiation of tumor-bearing mice resulted in tumor cell production of the type 1 interferon IFNβ which, in turn, induced CCL2, CCL7, and CCL12 and chemoattracted CCR2+ M-MDSC to the tumor microenvironment." (PMID 31001479, 2019). "Diverse chemokines, i.e., CCL2 (MCP-1), CCL5 (RANTES), CCL7 (MCP-3), CXCL8 (IL-8), and CXCL12 (SDF1), released by tumor cells induce migration, differentiation, and survival of tumor-infiltrating myeloid cells." (PMID 29686671, 2018). "Similar to MDSCs, TAMs and TANs are recruited to tumor sites by tumor-derived chemokines and growth factors, including CCL2/MCP-1, CXCL1/Gro-a, CCL7/MCP-3, CCL5/RANTES, CXCL8/IL-8, VEGF, PDGF, and M-CSF/CSF-1." (PMID 29735917, 2018). "Mɸ are recruited into irradiated tumour tissue at both acute and late stages through Mø/Mɸ chemoattractants CCL2, CCL5, CCL7, CCL8, CXCL12, VEGF and CSF-1." (PMID 30178305, 2018). "Often released by tumor or macrophages for local suppression of anti-tumor immune responses, including TGF-β, CCL5, CCL7, CXCL8, IDO, etc." (PMID 29299180, 2017). "For example, tumor secrete ligands CCL5, CCL7, and CXCL8, bind to their receptors CCR1 or CXCR2 expressed on subtypes of MDSCs, and attract MDSCs in the tumor microenvironment." (PMID 29299180, 2017).